EGFR (epidermal growth factor receptor)
Diseases named in the same sentence as EGFR in open-access papers (continued):
Sharing a sentence is not in itself a finding about the gene and the disease.
lung adenocarcinoma (continued). "Taken a glance in the BENEFIT study, the lung adenocarcinoma patients with concurrent mutations in EGFR and other oncogenes, including KRAS, had significantly shorter PFS than those with EGFR mutations only (13.2 months VS 4·7 months, HR 2.66, 95% CI 1.58–4.49; p = 0.0003)." (PMID 32505185, 2020). "In addition, the CA9 SNP rs2071676 AG + GG genotype were significantly correlated to the lower tumor stage of lung adenocarcinoma in the whole study population (p = 0.044) and EGFR wild type individuals (p = 0.033)." (PMID 32365566, 2020). "Materials and Methods: 591 cases of lung adenocarcinoma patients in Hebei Tumor Hospital who had undergone EGFR gene detection and DNA quantitative analysis were collected from January 2012 to August 2018.They were divided into two groups: EGFR mutant group and non-mutant group." (PMID 32127953, 2020). "A previous study reported that dose de-escalation of afatinib did not affect its efficacy in treating patients with advanced lung adenocarcinoma harboring EGFR mutations." (PMID 33113888, 2020). "Thus, the aim of this study is to evaluate the role of both AM and IM in the development of EGFR mutant driven lung adenocarcinoma." (PMID 32125091, 2020). "In the present study, we aim to clarify the relationship between CD44 polymorphisms and susceptibility to lung adenocarcinoma with or without EGFR mutations." (PMID 32344833, 2020). "We found that EGFR expression, STAT3, and the thickness of the stratum corneum (both in millimeters and in number of skin layers) had a statistically significant correlation with an adequate response to treatment with EGFR inhibitors in patients with stage IV lung adenocarcinoma." (PMID 33015988, 2020). "It is well known that lung adenocarcinomas with or without EGFR mutations have shown different drug effects against EGFR inhibitors." (PMID 32127953, 2020). "Therefore, we compared the efficacies of ICIs for the treatment of lung adenocarcinoma with ALK rearrangement and other oncogene drivers, including EGFR mutations." (PMID 32283823, 2020). "Mutations in cancers other than HCC associated with a negative outcome for ICI treatment include inactivating mutations in JAK1/2 or beta-2-microglobulin in melanoma, MDM4 amplifications, or EGFR alterations in different stage IV tumors or STK11/LKB1 alterations in KRAS-mutant lung adenocarcinoma." (PMID 33353145, 2020). "Salvage anlotinib might be a reasonable choice in EGFR wild-type lung adenocarcinoma after failure of chemotherapy." (PMID 33031343, 2020). "Several reports have shown that curcumin inhibits EGFR signaling via suppression of EGFR expression, induction of EGFR degradation, inhibition of kinase activity of EGFR, and modulation of EGFR dimerization in lung adenocarcinoma, colon cancer, and epidermoid carcinoma cell lines." (PMID 33246423, 2020). "According to the NCCN guidelines, patients with lung adenocarcinoma without EGFR mutations or patients for whom molecular targeted therapy was unsuccessful are candidates for conventional chemotherapy." (PMID 33167343, 2020). "Our results indicated that one reason why findings regarding the relationship of the EGFR structural status with the prognosis of early-stage lung adenocarcinoma differed in past reports is that genomic instability cannot be evaluated using the EGFR structural status alone." (PMID 32277151, 2020). "Notably, in a Japanese cohort study, strong ERβ expression predicted favorable clinical outcomes in patients with lung adenocarcinoma after treatment with EGFR TKIs." (PMID 33585221, 2020).
lung adenocarcinoma (continued). "Our results demonstrated that PD-L1 did not affect the efficacy of first-line EGFR-TKIs in metastatic EGFR mutated lung adenocarcinoma." (PMID 32092879, 2020). "Materials and Methods: We conducted a single-center retrospective study of 282 patients with early or locally advanced lung adenocarcinoma, with or without EGFR mutations, who underwent definitive therapy." (PMID 32523650, 2020). "But it is not very clear if EGFR mutation status affects the biological behavior of lung adenocarcinoma, because tumor gene regulation is very complicated and can be affected by many factors." (PMID 32127953, 2020). "Indeed, epidemiological statistics indicate that EGFR and KRAS mutations are present in ~ 50% of lung adenocarcinomas, of which ~ 20% are EGFR mutations and 26% KRAS mutations." (PMID 33060649, 2020). "However, the median overall survival (OS) has recently been increasing in patients with epidermal growth factor receptor (EGFR)-mutant lung adenocarcinoma and brain metastases due to the introduction of targeted therapy." (PMID 32298306, 2020). "However, the correlation between B7-H3-induced signaling and EGFR signaling, and between B7-H3-targeted immunotherapy and EGFR-targeted therapy in lung adenocarcinoma, remains to be elucidated." (PMID 33426073, 2020). "Combining SUVmax with other clinicopathological features could forecast the EGFR status in lung adenocarcinoma with unavailable EGFR gene testing." (PMID 32742498, 2020). "Epidermal growth factor receptor (EGFR) mutations account for 51.4% of advanced lung adenocarcinoma driver mutations in Asia and 15% to 22% in non-Asia area." (PMID 33194721, 2020). "It promotes the resistance of EGFR-TKIs in EGFR-mutant lung adenocarcinoma (LUAD)." (PMID 32294625, 2020). "Herein, we analyze B7-H3-induced signaling and its potential correlation with EGFR signaling in lung adenocarcinoma H3255 (L858R) and HCC827 (Del E746-A750) cells and explore the promising combination of B7-H3-targeted immunotherapy and EGFR-targeted therapy in lung adenocarcinoma." (PMID 33426073, 2020). "Whether CEA can serve as an effective marker for monitoring TKI treatment in EGFR-mutant lung adenocarcinoma is questionable because CEA heterogeneity may lead to contradictory results from different studies." (PMID 32034239, 2020). "EGFR mutations have been found to predominantly occur in patients with lung adenocarcinoma and are more frequent in female patients and nonsmokers." (PMID 32344833, 2020). "Herein we find that knockout of B7-H3 gene decreased cell survival and increased EGFR-tyrosine kinase inhibitor gefitinib susceptibility of both H3255 and HCC827 cells, two lung adenocarcinoma cell lines harboring EGFR L858R (exon 21) and Del E746-A750 (exon 19) mutations, respectively." (PMID 33426073, 2020). "Combining bmSUVmax with other clinicopathological features could forecast the EGFR status in lung adenocarcinoma with unavailable EGFR gene testing." (PMID 32742498, 2020). "So it is controversial and unclear if and how different EGFR mutation status affects the biological behavior of lung adenocarcinoma without using EGFR-TKI." (PMID 32127953, 2020). "Second, we only studied the effect of treatment on the prognosis of patients with lung adenocarcinoma and an EGFR mutation status and did not consider the influence of other genes." (PMID 33262942, 2020). "Considering these situations, the second purpose of this study was to clarify whether EGFR network expression profiles can be used to predict the prognosis of early-stage lung adenocarcinoma." (PMID 32277151, 2020). "More interestingly, Bie and colleagues found that FGL1 affected the proliferation of lung adenocarcinoma cells by regulating the expression of vascular endothelial growth factor, hypoxia-inducible factor, insulin-like growth factor, and EGFR through functional experiments and RNA sequencing." (PMID 32778129, 2020).
lung adenocarcinoma (continued). "In addition, our analyses of clinical samples confirmed that high Mig-6 expressions positively correlate with a poor prognosis and EGFR-TKI resistance in lung adenocarcinoma." (PMID 32552717, 2020). "Liquid biopsy of cerebrospinal fluid (CSF) and sequencing of cell-free DNA has rarely been used to identify epidermal growth factor receptor (EGFR) mutations, which can guide the design of precise, personalized treatment for patients with leptomeningeal metastasis from lung adenocarcinoma." (PMID 33120820, 2020). "However, SUVmax of primary tumors and regional lymph nodes didn't seem significantly different between two EGFR status lung adenocarcinomas." (PMID 32742498, 2020). "EGFR mutations have been found to occur more frequently in the female and nonsmoking populations and mainly occur in patients with lung adenocarcinoma in the Asian population." (PMID 32781755, 2020). "A total of 35 direct smear preparations diagnosed as lung adenocarcinoma and EGFR mutation negative were involved in this study." (PMID 33425389, 2020). "The representative cell model chosen for this purpose is the H1975 human lung adenocarcinoma cell line that was established from a non-smoker patient and possesses a mutation in the gene that confers resistance to EGFR inhibitors." (PMID 32599967, 2020). "Clinical and pathological characteristics of 103 patients with EGFR mutant lung adenocarcinomas." (PMID 33585221, 2020). "First, follow-up and survival analysis were not performed, so we are not sure if EGFR mutation status in advanced lung adenocarcinoma is an independent factor affecting prognosis." (PMID 32127953, 2020). "In this study, the high incidence of coexisting KRAS and EGFR driver mutations and the lower than expected IDH1/2 VAF suggest that IDH1/2 mutations may be branching drivers promoting subclonal progression of lung adenocarcinomas." (PMID 32333643, 2020). "We have first conducted a mutant proteomic analysis for clinical tissue specimens of 36 lung adenocarcinoma patients who harbored distinct EGFR mutations, Ex21 L858R, Ex19del, and no L858R/Ex19del." (PMID 32983988, 2020). "Furthermore, we detected mitochondria-accumulated EGFR in patient-derived EGFR-positive lung adenocarcinoma cells (PF001 and PF002)." (PMID 31936895, 2020). "Of special interest, this ratio increased to 5–7% for lung adenocarcinoma patients without EGFR/KRAS/BRAF/ALK mutations." (PMID 32677962, 2020). "Furthermore, a database analysis using The Cancer Genome Atlas revealed that the higher FGFR4 expression level was correlated with poor survival rates in wild-type EGFR lung adenocarcinoma." (PMID 32781755, 2020). "The data indicate that both FGFR4 SNPs rs2011077 and rs351855 may be associated with reduced presence of distant metastasis in Taiwanese patients with lung adenocarcinoma, especially those with the wild-type EGFR gene." (PMID 32781755, 2020). "In summary, anlotinib might be effective in EGFR wild-type lung adenocarcinoma after failure of chemotherapy." (PMID 33031343, 2020). "Indeed, the different sex distribution of the EGFR status in patients with lung adenocarcinoma is found in Taiwan." (PMID 32344833, 2020). "This study aimed to unveil profiles of mutant proteins expressed in lung adenocarcinomas of 36 patients harboring representative driver EGFR mutations (Ex19del, nine; L858R, nine; no Ex19del/L858R, 18)." (PMID 32983988, 2020). "In addition, Although follow-up time is short, the EGFR impact score also predicted prognosis in early-stage lung adenocarcinoma." (PMID 32277151, 2020). "EGFR mutation is very common in lung adenocarcinoma, but it has not been reported in this tumor owing to the rarity of the disease and lack of attempts to characterize it molecularly." (PMID 32505185, 2020).
lung adenocarcinoma (continued). "Using in silico analysis of the TCGA database, we found that lung adenocarcinoma patients bearing wild-type EGFR with the higher FGFR4 expression level is correlated with poor overall survival rates and five-years survival rates compared with those with lower FGFR4 expression patients." (PMID 32781755, 2020). "We aimed to explore if EGFR mutation status is related with tumor malignant degree by investigating the relevance of EGFR mutation status with DNA content and aneuploid peaks of lung adenocarcinoma cells in pleural fluids without using EGFR-TKIs." (PMID 32127953, 2020). "Moreover, overexpression of DSG2 in lung adenocarcinoma and squamous cell carcinoma cells activates EGFR and increases cancer cell proliferation and migration by c‐Src and EGFR‐dependent manner." (PMID 32997416, 2020). "Through this study, prognostic meaningful lung adenocarcinoma subtypes which are independent of EGFR and ALK mutations and the relevant mutational and expressional profiles were identified." (PMID 31987030, 2020). "In the current study, we investigated the relationship between CD44 polymorphisms and the susceptibility to lung adenocarcinoma with or without epidermal growth factor receptor (EGFR) gene mutations." (PMID 32344833, 2020). "But few researches evaluated the biological behavior of lung adenocarcinoma with or without EGFR mutations using DNA content detected by automatic DNA image cytometry." (PMID 32127953, 2020). "It is found that HCT could induce apoptosis of human lung adenocarcinoma A549 cells by the inhibition of EGFR gene transcription in vivo study." (PMID 32595734, 2020). "We retrospectively reviewed 1,020 subjects (mean age: 66.8 years, female: 41.7%) who were diagnosed with advanced lung adenocarcinoma, had EGFR mutation data, and did not undergo surgery from five medical institutes between 2010 and 2016." (PMID 32053675, 2020). "Therefore, our study can reasonably conclude that MPLA tumours with EGFR mutations and ALK positivity have imaging patterns similar to single lung adenocarcinomas." (PMID 32690092, 2020). "Notably, about 3% to 10% of ‘epidermal growth factor receptor’ (EGFR)-mutant lung adenocarcinoma transform into SCLC." (PMID 31108964, 2019). "Advanced epidermal growth factor receptor (EGFR)-mutant lung adenocarcinoma had a high overall incidence of brain metastasis during the full course, and local brain radiotherapy combined with systemic targeted therapy may be a better strategy." (PMID 31109441, 2019). "The presence of activating EGFR mutations, mainly in exons 18, 19, 20 and 21, which correspond to the tyrosine kinase domain, sensitizes lung adenocarcinomas to treatment with anti-EGFR tyrosine kinase inhibitors (TKi), such as erlotinib, gefitinib, afatinib, dacomitinib and osimertinib." (PMID 30824880, 2019). "Previous studies indicated that the epithelial–mesenchymal transition regulator, Slug, confers resistance to EGFR-TKI therapy in lung adenocarcinoma patients and that interleukin (IL)-8 plays a role in the EGFR-TKI-resistance mechanism by regulating cancer stem cell properties." (PMID 30609749, 2019). "We found that the GGO volume percentage was significantly higher in patients with primary lung adenocarcinomas with EGFR mutation compared with those without EGFR mutation." (PMID 30956990, 2019). "This study was aimed at investigating the prognostic significance of Baculoviral IAP repeat containing 5 (BIRC5) in lung adenocarcinoma (LAD) lacking EGFR, KRAS, and ALK mutations (triple-negative (TN) adenocarcinomas)." (PMID 31093306, 2019). "Real-time polymerase chain reaction (PCR) analysis showed that the right lower adenocarcinoma had an epidermal growth factor receptor (EGFR) mutation presenting as point mutation T790M in exon 20, while the left lower lung adenocarcinoma had a point mutation in exon 21 of EGFR." (PMID 31426797, 2019). "USP22 promotes resistance to EGFR-TKIs by stabilizing EGFR in EGFR-mutant lung adenocarcinoma." (PMID 31133011, 2019).
lung adenocarcinoma (continued). "EGFR sensitive mutations have been associated with similar clinical characteristics to TTF-1 positive expression in patients with lung adenocarcinoma, particularly among women and non-smokers." (PMID 31196060, 2019). "Our analysis of large transcriptomic dataset identified higher expression levels of CD47 mRNA, but not of CRT mRNA, in primary lung adenocarcinomas with EGFR mutations as compared to those with different oncogenic mutations." (PMID 32082304, 2019). "Patient 6 was initially diagnosed as lung adenocarcinoma harboring EGFR A763_Y764insFQEA." (PMID 31208370, 2019). "Thus, this multicenter retrospective study is performed to investigate the safety and efficacy of Apatinib Mesylate in advanced lung adenocarcinoma patients after failure of prior EGFR-TKI treatment." (PMID 31570733, 2019). "EGFR mutations are found in 10–15% of lung adenocarcinomas in the US and are enriched in tumors from never or former smokers." (PMID 31291990, 2019). "Then, we investigated whether a mTOR signaling inhibitor (BEZ235) could influence EGFR-TKI sensitivity in lung adenocarcinoma cells." (PMID 31801598, 2019). "In conclusion, our study indicates that Apatinib Mesylate may have good therapeutic efficacy in treating patients with advanced progressed lung adenocarcinoma with EGFR-TKI resistance, and the adverse events can likely be controlled." (PMID 31570733, 2019). "To illustrate the clinical importance of our findings, we evaluated MHC-I expression in a patient who presented with an epidermal growth factor receptor (EGFR) mutant lung adenocarcinoma that subsequently transformed to SCLC following treatment with the EGFR inhibitor Erlotinib." (PMID 31564637, 2019). "Mutations in EGFR (epidermal growth factor receptor 1) and KRAS (Kirsten rat sarcoma viral oncogene homolog GTPase) and ALK (anaplastic lymphoma kinase) rearrangements are mostly found in lung adenocarcinoma, accounting for 30–40% of NSCLCs." (PMID 31795465, 2019). "Serum IGFBP7 levels before EGFR-TKI treatment could predict PFS with EGFR-TKI treatment in patients with EGFR-mutant lung adenocarcinoma." (PMID 30609749, 2019). "In the 34 patients with stage IV lung adenocarcinoma treated with a first-line EGFR TKI (Table A3), those with concordant EGFR mutation test results in liquid/tissue biopsy had significantly poorer PFS than those with discordant results (p = 0.0032) (Figure A1a)." (PMID 31652678, 2019). "Thus, we investigated the frequency of EGFR and KRAS mutations in a large Brazilian series of lung adenocarcinoma together with patients’ genetic ancestry, clinicopathological and sociodemographic characteristics." (PMID 30824880, 2019). "H441-L2G cells (lung adenocarcinoma cells with wild-type EGFR, which express the L2G fusion construct containing dual optical reporters (firefly luciferase 2 and eGFP)) were subcutaneously injected into NOD/SCID mice for in vivo validation of WA-mediated anticancer effects." (PMID 31319622, 2019). "EGFR mutation-positive lung adenocarcinoma patients who were treated with gefitinib, a first-generation EGFR-TK inhibitor (EGFR-TKI), had better outcomes than those without EGFR mutations." (PMID 30790152, 2019). "In this study, we demonstrated that TTF-1 expression was a good prognostic indicator for OS and PFS in patients with stage IV lung adenocarcinoma regardless of the presence or absence of EGFR mutations." (PMID 31196060, 2019). "The molecular profiles of NSCLC have been extensively analyzed, and revealed that activating mutations in the epidermal growth factor receptor gene (EGFR) are found in approximately 10–15% of Caucasian patients and 30–40% of Asian patients with lung adenocarcinoma." (PMID 30808329, 2019). "The presented results indicate that radiomics-based nomogram may potentially facilitate scalable precision medicine on identifying eligible patients of lung adenocarcinoma for EGFR-targeted therapy." (PMID 31993370, 2019).